PCBP1 (poly(rC) binding protein 1)
Diseases named in the same sentence as PCBP1 in open-access papers (continued):
Sharing a sentence is not in itself a finding about the gene and the disease.
Anxiety (1 paper, 2024). Intense feelings of nervousness, tension, or panic often arise in response to interpersonal stresses. "Our study confirms the potential of PCBP1 treatment as a therapeutic option for PD, as it shows therapeutic efficacy in both motor‐deficiency and anxiety during PD progression." (PMID 38376022, 2024). "The effects of PCBP1 treatment on the non‐motor symptom of 6‐OHDA‐induced anxiety was evaluated using the OFT." (PMID 38376022, 2024). "In the OFT, PCBP1 exhibited significant improvements in behavioral abnormalities and reduced anxiety in the PD model rats (p < .01)." (PMID 38376022, 2024).
atherosclerosis (1 paper, 2020). A disease characterized by the build-up of fatty material and calcium deposition in the arterial wall resulting in partial or complete occlusion of the arterial lumen. "On this basis, present study uncovered that SNHG1 attenuated atherosclerosis via up-regulating GNAI2 and PCBP1." (PMID 32536864, 2020).
cardiac tumour (1 paper, 2007). "Then the up-regulation of PCBP1 may regulate the cap-independent mechanism of translation initiation of cardiac tumour-associated genes in the development of GCA." (PMID 17927838, 2007).
epilepsy (1 paper, 2026). A brain disorder characterized by episodes of abnormally increased neuronal discharge resulting in transient episodes of sensory or motor neurological dysfunction, or psychic dysfunction. "We identify and validate ferroptosis-related genes (e.g., FTH1, FTL, PCBP1) as potential biomarkers and therapeutic targets, supported by congruent biochemical evidence of oxidative stress in this drug-resistant epilepsy." (PMID 42051157, 2026).
esophageal cancer (1 paper, 2022). A primary or metastatic malignant neoplasm involving the esophagus. "Here, we found overexpressed PCBP1 in esophageal cancer tissues by quantitative polymerase chain reaction (qPCR) and western blotting analysis." (PMID 35287546, 2022).
gall bladder carcinomas (1 paper, 2022). "Besides, PCBP1 was considered as a mediator that played a role in TGF-β-induced EMT in gall bladder carcinomas." (PMID 35100974, 2022).
Hepatic steatosis (1 paper, 2020). Steatosis is a term used to denote lipid accumulation within hepatocytes. "Although PCBP1-deleted hepatocytes are iron-deficient, the supplementation of iron dose doesn’t inhibit the hepatic steatosis, indicating that hepatic steatosis may not require iron deficiency." (PMID 33117818, 2020). "Mice lacking Pcbp1 in hepatocytes show defects in iron homeostasis and develop liver disease with hepatic steatosis, inflammation, and degeneration." (PMID 33117818, 2020).
hereditary spastic paraplegia (1 paper, 2017). Hereditary spastic paraplegias (HSP) comprise a genetically and clinically heterogeneous group of neurodegenerative disorders characterized by progressive spasticity and hyperreflexia of the lower limbs. "Interestingly, next to the clear presence of neuronal transcripts among the identified PCBP1 targets we identified known genes associated with hereditary peripheral neuropathies and hereditary spastic paraplegias." (PMID 28077174, 2017). "Besides the clear presence of neuronal transcripts seen among the mRNA targets containing PCBP1 recognition motifs, we identified known genes associated with hereditary peripheral neuropathies and hereditary spastic paraplegias." (PMID 28077174, 2017).
HIV-1 infection (1 paper, 2022). The type species of lentivirus and the etiologic agent of acquired immunodeficiency syndrome (AIDS). "These include host cell co-factor proteins that facilitate HIV-1 infection, such as BANF1 (O75531), importin (O95373), NPM1 (P06748), SNW domain-containing protein 1 (Q13573), and PCBP1 (Q15365)." (PMID 36325020, 2022).
intervertebral disc degeneration (1 paper, 2023). "The immunofluorescence results indicate a significant increase in the expression levels of NCOA4 and PCBP1 proteins, while the expression level of GPX4 protein was decreased in human intervertebral disc degeneration tissues." (PMID 37736497, 2023).
iron deficiency (1 paper, 2025). "Given our finding that reduced iron availability enhances PCBP1 RNA interactions, PCBPs could similarly contribute to translational repression during iron deficiency." (PMID 41036621, 2025).
iron overload (1 paper, 2022). "Investigations of TF, FTL, PCBP1 and VDAC3 and their different specificities in terms of their roles in iron metabolism, independent of lipid-lowering treatment actions, may also be of high interest in the treatment of iron overload and deficiency." (PMID 35181730, 2022).
liver disease (1 paper, 2020). "Overall, these findings suggest that PCBP1 plays a complex role in the regulation of ferroptosis-related liver disease." (PMID 33117818, 2020).
melanoma (1 paper, 2020). A malignant, usually aggressive tumor composed of atypical, neoplastic melanocytes. "Li also showed that high PCBP1 expression is associated with low expression of immune checkpoint signals in melanoma." (PMID 32245497, 2020). "However, melanoma with low PCBP1 expression responds better to anti-PD-1 therapy, suggesting that, in this ICI-sensitive tumor, the Teff-Treg commitment program sensitizes tumors for ICI treatment." (PMID 32245497, 2020).
microcytic anemia (1 paper, 2023). Anemia in which the red blood cell volume is decreased. "In PCBP1-depleted cells, this ferritin iron accumulation was impaired and associated with diminished heme and hemoglobin synthesis, which in the animal led to a microcytic anemia typical of iron deficiency." (PMID 36818045, 2023). "In a mouse model of inducible PCBP1 deletion, mice developed microcytic anemia that was traced to a defect in PCBP1-mediated ferritin iron storage." (PMID 36818045, 2023).
neuroblastoma (1 paper, 2017). Neuroblastoma (NB) is the most common solid, extracranial childhood tumor. "In addition, we assessed the expression of PCBP1 in differentiated neuroblastoma cell lines expressing either wild type or mutant HSPB1 (P182L or R127W)." (PMID 28077174, 2017).
neuropathy (1 paper, 2017). A disorder affecting the nervous system that manifests with pain, tingling, numbness, and/or muscle weakness. "Nevertheless, precautions have to be made when linking PCBP1 to the expression levels of the identified neuropathy genes." (PMID 28077174, 2017). "Looking at the strong potential of PCBP1 to control the fate of many mRNAs, it is not surprising that it also controls transcripts important for neuronal processes and consequently known neuropathy genes." (PMID 28077174, 2017).
oral cancers (1 paper, 2015). "In the oral cancers, hsa-miR-21 was found to be up-regulated while its target genes PCBP1 and PCBP2 were found to be down-regulated." (PMID 26064958, 2015).
Parkinson disease (1 paper, 2024). A progressive degenerative disorder of the central nervous system characterized by loss of dopamine producing neurons in the substantia nigra and the presence of Lewy bodies in the substantia nigra and locus coeruleus. "Previous studies have suggested a potential link between poly(rC)‐binding protein 1 (PCBP1) and neurodegenerative diseases, including Parkinson's disease (PD)." (PMID 38376022, 2024).
renal carcinoma (1 paper, 2018). A carcinoma arising from the epithelium of the renal parenchyma or the renal pelvis. "E. Kaplan-Meier survival curve of renal carcinoma patients with different expression level of PCBP1." (PMID 30086790, 2018).
renal fibrosis (1 paper, 2024). A final common manifestation of a wide variety of chronic kidney diseases characterized by glomerulosclerosis and tubulointerstitial fibrosis. "Our results also suggest Pcbp1 as an intervention target in aging‐related renal fibrosis and highlight Rutin as a potential therapeutic agent in mitigating age‐related renal chronic low‐grade inflammation and fibrosis." (PMID 39016438, 2024).
Sepsis (1 paper, 2026). Sepsis is defined as life-threatening organ dysfunction caused by a dysregulated host response to infection. "FOXO1, KLHL3, and PCBP1 were weakly expressed in the sepsis group whereas MTF1, TMEM59, PIK3CB, and S100A9 were highly expressed in the sepsis group." (PMID 41542228, 2026). "qPCR results showed that the expression of S100A9, PCBP1, PIK3CB, FOXO1, and TMEM59 was consistent with the public dataset, among which S100A9, PIK3CB, and TMEM59 were significantly overexpressed in sepsis, whereas PCBP1 and FOXO1 were significantly underexpressed in sepsis." (PMID 41542228, 2026).
tumor (49 papers, 2008 to 2026). "In the larger-sample-size TCGA cohort, it also showed a higher mutation frequency of APC and PCBP1 in KRAS-Mut samples than in WT tumor samples (adjusted chi-square test, P < 0.05)." (PMID 35836817, 2022). "In this study, we provided convincing evidence that human PCBP1 profoundly regulates the splicing of genes associated with tumour metastasis." (PMID 34857818, 2021). "We found that genes whose transcriptional level is regulated by PCBP1 and regulated alternative splicing events (RASEs) affected by PCBP1 are associated with tumour metastasis." (PMID 34857818, 2021). "The overall analysis showed that low PCBP1 levels were significantly associated with tumor stages (p < 0.01), clinical stages (p < 0.05), lymph node and distant metastasis (p < 0.05)." (PMID 32922440, 2020). "Given the tumor suppression effect of PCBP1 through p27 upregulation, we sought to unravel the underlying mechanism of p27 upregulation by PCBP1." (PMID 30086790, 2018). "Eventually, we also demonstrated that loss of PCBP1 mRNA and protein were positively related to p27 downregulation in clinical tumor samples, indicating the general importance of p27 loss in tumorigenesis." (PMID 30086790, 2018). "So far, the underlying mechanism of PCBP1 in tumor suppression remains elusive." (PMID 30086790, 2018). "PCBP1 staining in metastatic tumor tissue was observed at comparatively much less intensity, confirming in vivo loss of PCBP1 expression might play a role in promoting peritoneal metastasis." (PMID 29138420, 2017). "Taken together, our results uncover the tumorigenic mechanism of PCBP1 depletion and suggest that inhibition of tumor cell autophagy with autophagic inhibitors could be an effective therapeutical strategy for PCBP1-deficient tumor." (PMID 32922440, 2020). "PCBP1 knockdown significantly enhanced tumor metastasis compared to control cells, as shown in lung and liver metastasis models." (PMID 41117067, 2025). "In lung adenocarcinoma research, it has been observed that increasing the levels of the RBP PCBP1 slows tumor growth, migration, and invasion." (PMID 40271197, 2025). "PCBP1 fulfills this tumor-suppressing role by stabilizing DKK1 mRNA and hindering the Wnt/β-catenin signaling pathway." (PMID 40271197, 2025). "It has been shown that depletion of PCBP1 leads to iron accumulation and inhibits tumor growth by blocking p62 degradation." (PMID 39845670, 2024). "Carbon ions decreased the expression of PCBP1 in A549 cells, and low expression of PCBP1 inhibited tumor proliferation by promoting ferroptosis." (PMID 39845670, 2024). "The expression of all six FRGs was significantly different (p < 0.05), with FTH1, FTL, and PCBP1 being overexpressed in the tumor group and ZFP36, NCOA4, and TNF expressed less in the tumor group." (PMID 37555866, 2023). "Our lab has previously characterized a PCBP1-dependent mechanism of tumor suppression that involves the inhibition of mRNA translation." (PMID 37927213, 2023). "Poly C binding protein (PCBP1), a tumor suppressor, promotes tumor cell apoptosis during starvation by downregulating LC3B and repressing autophagy." (PMID 37446120, 2023). "On the other hand, poly(rC)-binding protein 1 is an RNA-binding protein that can function as a tumour suppressor, having been found to be downregulated in many cancer types." (PMID 38203548, 2023). "The poly(rC) binding protein 1 gene (PCBP1) encodes the heterogeneous nuclear ribonucleoprotein E1 (hnRNPE1), a nucleic acid-binding protein that plays a tumor-suppressive role in the mammary epithelium by regulating phenotypic plasticity and cell fate." (PMID 37927213, 2023). "Another interesting paper showed that poly C binding protein 1 (PCBP1), a novel tumor suppressor gene, withdraws or balances the basal cell autophagy necessary to retain cell homeostasis in CRC cells." (PMID 37373349, 2023).
tumor (continued). "Tumor sections were subjected to qRT‐PCR and immunohistochemical staining to analyze the expression of circMAP2K2, PCBP1 and GPX1 in the xenograft tumors." (PMID 37752765, 2023). "Poly(rC) binding protein 1 (PCBP1) has been demonstrated previously to be a PCa tumour suppressor gene." (PMID 36033512, 2022). "In the present study, we demonstrated that intended over-expression of PCBP1 attenuated the tumor growth and metastasis mediated by C12orf48, suggesting that altered PCBP1 expression is responsible for regulating cellular processes downstream C12orf48." (PMID 35100974, 2022). "The hnRNP family was significantly downregulated in tumour tissues, while PCBP1 exhibited the most significant differential expression between the early death group and the long-term survival group." (PMID 35907982, 2022). "Other works in various human cancer cells uncovered that PCBP1 binds to p27 mRNA 3’-UTR region via 5’-AUUAAGUAAU-3’ to repress tumor cell transformation and carcinogenesis." (PMID 35287546, 2022). "Through data analysis, we found that the expression of PCBP1 in patients with long survival time was higher than that in patients with short survival time, and the expression of PCBP1 in tumor tissues was significantly different from that in normal tissues." (PMID 35907982, 2022). "Taken together, these results show that PCBP1 acts as a tumour suppressor gene, inhibiting the tumorigenesis of LUAD." (PMID 35907982, 2022). "Since the reduction of PCBP1 is a key alteration contributing to the acquisition of metastatic characteristics in tumour cells, understanding the function of PCBP1 is critical for its development as a therapeutic target to slow cancer progression." (PMID 35907982, 2022). "From above, these studies strongly suggested that PCBP1 was a tumor suppressor and had the capacity of attenuating tumorigenicity of cancer cells." (PMID 35100974, 2022). "Taken together, these results reveal that PCBP1 acts as a tumour suppressor gene, inhibiting the tumorigenesis of LUAD." (PMID 35907982, 2022). "PCBP1 acts as a novel tumor suppressor gene in many cancers and is characterized by the downregulation and inhibition of tumor formation and metastasis." (PMID 36452487, 2022). "Tumour growth was substantially inhibited in the PCBP1 overexpression group, as shown by the smaller tumour size and lighter tumour weight." (PMID 35907982, 2022). "PCBP1 has been shown to be a tumour suppressor and is closely related to the occurrence and development of various tumours." (PMID 35907982, 2022). "In the subcutaneous xenograft model, tumours appeared to have larger tumour volumes in the PCBP1 knockdown groups than in the control groups." (PMID 35907982, 2022). "PCBP1 expression was significantly higher in tumor samples from oxaliplatin-refractory patients than in those from oxaliplatin-responsive patients." (PMID 37303491, 2022). "PolyC-RNA-binding protein 1 (PCBP1) functions as a tumour suppressor and RNA regulator that is downregulated in human cancers." (PMID 35907982, 2022). "The PCBP1 gene, which encodes an RBP, is located on human chromosome 2 (2p13-12), which is described as a tumour suppressor gene region." (PMID 34857818, 2021). "Their results showed that PCBP1 regulates the alternative splicing of STAT3 exon 23 to promote the transformation of oncogenic subtype STAT3α to the tumour suppressor subtype STAT3β14." (PMID 34857818, 2021). "We found that the expression level of PCBP1 in tumour tissues was higher than that in adjacent tissues (P = 5.2e−04)." (PMID 34857818, 2021). "In a variety of tumour cell lines, PCBP1 promotes the transformation of oncogenic subtypes to tumour suppressor subtypes by inhibiting the alternative splicing of an important intermediate molecule, thereby affecting tumour invasion." (PMID 34857818, 2021).